NF1 (neurofibromin 1)
Diseases named in the same sentence as NF1 in open-access papers (continued):
Sharing a sentence is not in itself a finding about the gene and the disease.
melanoma (continued). "The most common activating genetic alterations in melanoma include v-Raf murine sarcoma viral oncogene homolog B (BRAF) (~50%), RAS viral oncogene homolog (RAS) (~25%) and Neurofibromin 1 (NF1) (~15%) mutations." (PMID 35565222, 2022). "The most prevalent gene mutations identified in melanoma are B-RAF, RAS, and NF-1, all of which cause constitutive MAPK signaling." (PMID 35756619, 2022). "There is also an overlap in genes associated with melanoma and the RASopathies, in that mutations in BRAF, NRAS, and NF1 in melanoma are also well‐known RASopathy‐associated genes." (PMID 35266292, 2022). "Inactivating mutations in the NF1 gene are present in about 12–15% of melanomas, and are particularly frequent in high-CSD CMs, for example, lentigo maligna melanoma." (PMID 36143375, 2022). "Less frequent mutations in the NF1, RAC1, and PTEN genes were seen in the mut compared with wt patients from the 3-melanoma institution cohort." (PMID 34986841, 2022). "Collectively, these data suggest that combined immune checkpoint blockade and HDAC inhibition can stimulate T cell immunity against human UM in vitro and BRAF, NRAS, and NF1 wildtype melanoma in vivo." (PMID 34753889, 2022). "There are a handful of early genetic events linked to the development of melanoma in situ, including mutations in BRAF, NRAS, or NF1." (PMID 36143375, 2022). "For example, melanomas harboring mutations of driver events in the MAPK pathway (BRAF, NRAS, NF1, KIT, and so on) have been shown to respond well to MEK/MAPK inhibitors." (PMID 35844619, 2022). "The main melanoma driving mutations are part of ERK pathway, with BRAF mutations being the most frequent ones, followed by NRAS, NF1 and MEK mutations." (PMID 35941108, 2022). "Previous studies have shown the importance of NF1 in several other cancers, including glioblastoma, melanoma, breast, and lung cancers." (PMID 36163358, 2022). "The described pattern of NF1 mutant melanoma having the largest number of mutations within the three main subtypes of BRAF, NRAS, or NF1-mutated melanomas was apparent in our ARID1A mutated cohort." (PMID 35565222, 2022). "Ultraviolet radiation induces a range of gene alterations, including those in BRAF, RAS, C-Kit and NF1, and promotes the activation of inflammation in melanoma, according to accumulating evidence." (PMID 36498797, 2022). "The greatest evidence of this achieved so far is related to treatment with MEK inhibitors for NF1-mutant melanoma." (PMID 36232957, 2022). "Transcriptome sequencing analysis of tissue samples from melanoma patients indicated that mutations closely related to melanoma progression mainly included BRAF mutation, NRAS mutation and NF1 mutation." (PMID 36601121, 2022). "In contrast, melanomas with WT BRAF, NRAS and NF1 that are driven by activating KIT mutations can be treated with the RTK inhibitor imatinib, yielding response rates of 16–30%; however, most of these responses were partial and transient." (PMID 35234863, 2022). "Immunotherapy and targeted therapy are both found to be effective for the treatment of NF1-mutant melanoma; however, further studies are required to determine the best treatment protocol with minimal side effects." (PMID 36232957, 2022). "Both melanomas showed mutations in the TERT promoter region, and one additionally harbored an NF1 mutation." (PMID 36077603, 2022).
melanoma (continued). "Metastatic melanoma (MM) is a highly mutated type of cancer and can be classified into four groups depending on the driver mutation observed—mutation in BRAF (~50% of melanomas), NRAS (~30%), NF1 (10–15%) or triple wildtype." (PMID 34066022, 2021). "Accordingly, loss-of-function mutations of the NF1 protein result in hyper-activation of RAS and, in combination with mutant BRAF protein, prevent oncogene-induced senescence during melanoma development by deregulating the PI3K and MAPK pathways." (PMID 34576054, 2021). "A genetic screen of the whole-genome shRNA library led to the identification of two negative regulators of resistance to Vemurafenib in BRAFV600E-expressing melanoma cells: neurofibromin 1 (NF1) and CUL3." (PMID 33800394, 2021). "While KRAS is the overall dominant gene that is coaltered, HRAS contributed to most coalteration cases in bladder cancer, and NF1 coalteration preferably occurs in melanoma and endometrial cancer." (PMID 33507258, 2021). "For example, the treatment of melanoma cells with the combination of BRAF inhibitor and MEK inhibitor showed either a loss of NF1 expression or an acquired mutation." (PMID 34362135, 2021). "In particular, understanding the interaction during melanocyte development between NF1 and key signaling pathways, which are known to be reactivated in advanced melanoma, is still under investigation." (PMID 34362135, 2021). "These genomic subtypes include BRAF-mutant melanoma (50%), NRAS, KRAS and HRAS-mutant melanoma (25%), NF1-mutant melanomas (15%) and triple wild-type melanomas (10%)." (PMID 34572747, 2021). "The TCGA program subsequently undertook a multiplatform characterization of cutaneous melanoma samples at the DNA, RNA, and protein levels, in which NF1-mutant melanoma emerged as an important subtype within a genomic classification framework." (PMID 34331013, 2021). "In contrast, common mutations in melanomas such as NRAS and NF1 remain unable to be targeted to date." (PMID 34831002, 2021). "We collected information on the mutation status of BRAF, NRAS and NF1 genes for SKCM TCGA samples and investigated the association between isomiR expression and the most clinically relevant mutations in melanoma." (PMID 34698264, 2021). "As such, NF1 mutations together with RAS mutations and BRAF fusions, which have been described in mucosal melanomas and lead to increased activation of the MAPK pathway, are promising therapeutic targets for MEK inhibition." (PMID 35008570, 2021). "Increased signaling activity of the mitogen‐activated protein kinase (MAPK) pathway is a hallmark of melanoma and can be attributed to mutations in the BRAF, NRAS, KIT, or NF1 genes." (PMID 32767816, 2021). "Among the 14 tested drugs, each at their MTD, only the rapamycin family of mTOR inhibitors (rapalogs) showed selective activity against nf1/pten-mutant melanoma in vivo as single agents." (PMID 34331013, 2021). "Mutations cooperation between NF1 and BRAF was also described in melanocytic nevi to explain the bypass of oncogene-induced senescence (OIS) and the progression to transformed melanoma." (PMID 34362135, 2021). "With the emergence of high-throughput genomic technologies, several commonly mutated genes that play a central role in melanoma tumorigenesis and metastasis, such as BRAF, NRAS, and NF1, were identified." (PMID 33564068, 2021). "Clearly, a better understanding of the molecular pathogenesis of NF1-mutant melanomas is needed to improve the design and hence the outcome of treatments for this subtype of melanoma." (PMID 34331013, 2021).
melanoma (continued). "To assess the transplantation potential of our melanoma model, we isolated nf1/pten-mutant melanoma cells and transplanted them intraperitoneally into the optically clear immunodeficient rag2E450fs(casper) zebrafish (designated “rag2−/−”)." (PMID 34331013, 2021). "High-CSD melanomas include lentigo maligna type and desmoplastic melanomas, which often have a high mutation burden and can harbor NRAS, BRAFnon-V600E, or NF1 mutations." (PMID 34571969, 2021). "The absence of a cytotoxic effect and initiation of autophagy as a cell survival mechanism would likely limit the therapeutic potential of rapalogs in nf1/pten-mutant melanomas." (PMID 34331013, 2021). "Recent efforts to develop improved targeted therapies for melanoma have mainly focused on the BRAF-mutant subtype, leaving a paucity of treatment options for patients with NF1-mutant melanomas." (PMID 34331013, 2021). "To assess the durability of pathway suppression by inhibitor treatment, we treated nf1/pten-mutant-melanoma recipients with the inhibitors for 6 days, then analyzed the tumors after 4 days in the absence of the drugs." (PMID 34331013, 2021). "Under basal conditions, NF1 inhibits MAPK signalling and so in melanomas with a loss of function mutation in NF1, uncontrolled MAPK pathway activity can lead to tumorigenesis." (PMID 34066022, 2021). "The most frequent mutations seen in mucosal melanomas were in SF3B1 (27%), KIT (18%), and NF1 (17%)." (PMID 33724703, 2021). "It is unlikely that the FDA-approved BRAF-mutant-specific inhibitors will be beneficial against BRAF-wild-type, NF1-mutant melanomas." (PMID 34331013, 2021). "None of the drugs delayed tumor progression when given alone to 3-week-old fish-bearing nf1/pten-mutant melanomas, and only sirolimus in combination with venetoclax showed overall survival benefit compared to sirolimus alone." (PMID 34331013, 2021). "Even simultaneous inhibition of both pathways only transiently inhibited the growth of nf1/pten-mutant melanomas, such that the overall survival of tumor-bearing fish was unaffected." (PMID 34331013, 2021). "We also tested the three-drug combination identified in our NF1/PTEN-mutant melanoma model in BRAF-mutant melanomas with PTEN mutations, because BRAF activation by mutation is more prevalent than biallelic inactivating mutations of NF1." (PMID 34331013, 2021). "About 45% of melanomas, displaying wt BRAF and NRAS proteins, show mutation of the Neurofibromin 1 (NF1) oncosuppressor gene and loss of its control on Mitogen-Activated Protein Kinase (MAPK) activation." (PMID 34207514, 2021). "The nf1/pten-mutant melanoma cells grew rapidly in DMSO-treated recipients and progressed from an inoculum of 500 cells to readily detectable pigmented tumors at 4–8 days post transplantation." (PMID 34331013, 2021). "The overall frequency of main mutations in mucosal melanomas is as follows: NRAS (8%), BRAF (6%), neurofibromin 1 (NF1) (14%), KIT (13%), splicing factor 3b subunit 1(SF3B1) (15%)." (PMID 35008570, 2021). "Given the superiority of sirolimus in suppressing the growth of transplanted nf1/pten-mutant melanomas while inducing autophagy in normal tissues, we faced a major challenge: to identify drugs that could selectively cause apoptosis in sirolimus-sensitized melanoma cells." (PMID 34331013, 2021). "Sun-exposure-related melanoma has high melanocyte mutations such as NRAS, neurofibromin 1, KIT, and BRAFnonV600E compared with common mutation BRAFV600E in non-sun-exposed-related melanoma." (PMID 34199951, 2021).
melanoma (continued). "Using a zebrafish experimental system that models human NF1-mutant melanomas, we show that activation of both the RAS and PI3K pathways in a background of pten loss is required to initiate melanomas in nf1-deficient animals." (PMID 34331013, 2021). "The precise role played by the tumor suppressor gene NF1 in melanocyte biology and during the transformation into melanoma is not completely understood." (PMID 34362135, 2021). "Since NF1 serves as a negative regulator of RAS, the first protein in the MAPK signaling cascade, mutations that cause a loss of NF1 function have been implicated in constitutive MAPK activation and acquired resistance to BRAFi therapy in melanoma." (PMID 33807778, 2021). "Mutations in key genes of the MAPK/ERK pathway, namely NF1, NRAS and BRAF, identify three main molecular subtypes of melanoma." (PMID 34698264, 2021). "Among nine patients with somatic mutation testing performed on melanoma tumors, there were four NRAS Q61R mutations, three BRAF V600E mutations, and one loss-of-function NF1 mutation." (PMID 34262818, 2021). "Next, we analyzed C > T transitions in four mutational subtypes of melanoma, BRAF-, NRAS-, NF1-mutant samples and triple-wildtype samples." (PMID 33578810, 2021). "We also treated nf1/pten-mutant melanomas with everolimus and temsirolimus, two FDA-approved analogs of sirolimus." (PMID 34331013, 2021). "The three most prevalent genes mutated in melanoma are BRAF, neuroblastoma RAS viral oncogene homolog (NRAS), and neurofibromatosis 1(NF1), and all participate in the mitogen-activated protein kinase (MAPK) signaling cascade that regulates cell proliferation." (PMID 34066966, 2021). "By large-scale targeted sequencing, whole-exome sequencing (WES), and whole-genome sequencing (WGS), NF1 has been established as one of the key drivers of melanoma." (PMID 34123788, 2021). "Part of the investigational effort focuses on targeting downstream effectors or parallel pathways that are essential for NRAS and NF1 mutant melanomas, and another investigation is focused on the combined targeted therapy approach." (PMID 34831002, 2021). "Low-CSD melanomas have a moderate mutational burden and are associated with BRAFV600E mutations while high-CSD melanomas have a higher mutational burden and are associated with NRAS, NF1, and BRAFnonV600E mutations." (PMID 35008286, 2021). "NRAS and NF1 mutations are less frequent than BRAF mutations, occurring in approximately 10-25% and 14% of melanomas, respectively." (PMID 34025662, 2021). "The differences were further assessed by univariate logistic regression, and, after adjustment, only the mutations in NF1 and ROS1 remained independently associated with the CSD melanomas." (PMID 34680367, 2021). "In general, mutant NF1 melanoma contain WT BRAF and WT NRAS, and rather carry comutations in the so-called RASopathy genes (PTPN11 or RASA2)." (PMID 34362135, 2021). "The study partitioned melanoma tumors (both primary and metastatic) based on the pattern of the most prevalent mutated genes into four subtypes: BRAF, NRAS, NF1, and WT." (PMID 33564068, 2021). "The MAPK pathway is constitutively active in a large percentage of melanomas because of activating NRAS and BRAF mutations or inactivating NF1 mutations." (PMID 33766731, 2021).
melanoma (continued). "Regarding therapy, a study revealed Calpain1 (CAPN1), a calcium-dependent neutral cysteine protease, as a novel NF1 binding partner that regulates NF1 degradation in melanoma cells." (PMID 32850962, 2020). "Transcriptome-wide profiling of patient-derived melanoma samples has led to the identification of specific signatures associated with major oncogene subtypes (e.g., BRAF-mutant, NRAS-mutant, NF1-mutant, and triple wild-type) and prognoses." (PMID 33024276, 2020). "Neurofibromin 1 (NF1) deficiency overcame BrafV600E-induced senescence and conferred BRAF inhibitor resistance in melanoma." (PMID 31285545, 2020). "The NF1 gene was found, to be after BRAS and NRAS, to be the third most frequently mutated in melanoma." (PMID 32605090, 2020). "An actionable finding was evidenced in 51% of the included cases, and notably, four patients with an original diagnosis of soft tissue tumors were genotypically recategorized as NF1 and high TMB melanomas with UV-induced mutations." (PMID 32825562, 2020). "As recently reported, potential markers in melanoma are mutations (on BRAF, NRAS, KIT, GNA11/GNAQ, NF1, CDKN2AI, immunohistochemical biomarkers (such as PD-11 and PD-L1, as well as mutated BRAF and NY-ESO-1), miRNAs, and other serum molecules." (PMID 33302400, 2020). "Since 2000, a role for NF1 was proposed for the genesis of desmoplastic neurotropic melanoma, an uncommon melanoma with pathologic features in common with schwannomas." (PMID 32850962, 2020). "In the last decade, multiple large-scale sequencing studies have elucidated the genetic landscape of cutaneous melanoma and led to the classification of the genetic subtypes BRAF mutant, RAS mutant, NF1 mutant or triple wild-type melanoma." (PMID 32825510, 2020). "Various aberrations within the NF1 gene were found in 17% of samples in the Melanoma Genome Project report." (PMID 32605090, 2020). "Upon further characterization, it was demonstrated that SBI-756 impaired eIF4F complex formation in melanoma cells and inhibited the growth of BRAF, NRAS, and NF1-mutant melanoma cell lines." (PMID 32517051, 2020). "The MAPK pathway that is activated in melanoma as a result of mutations in BRAF, NRAS, or NF1 has been shown to regulate the expression, stability, and activity of a number of different melanoma-relevant transcription factors." (PMID 33024276, 2020). "The neurofibromin 1 (NF1) gene is considered one of the driver genes in melanomas, specifically in chronically sun-exposed or older subjects and in desmoplastic melanoma." (PMID 32054078, 2020). "Most reported MAP2K1 mutations have accompanied other driver mutations of melanoma including BRAF, NRAS, and NF1." (PMID 32483240, 2020). "Large-scale sequencing efforts have led to the classification of melanoma into four major subtypes (i.e., BRAF-mutant, NRAS-mutant, NF1-deficient, and triple wild-type)." (PMID 33024276, 2020). "The majority of melanomas harbor point mutations of BRAF, NRAS, KIT, or NF1 that drive tumor growth." (PMID 32123303, 2020). "The first three include melanomas harboring BRAF, NRAS, or neurofibromin 1 (NF1) mutations, respectively, and show constitutive activation of the MAPK pathway." (PMID 32466585, 2020). "Using a forward genetic screen, we identified loss of NF1 and CUL3 as drivers of vemurafenib resistance in melanoma, independently confirming results from similar genetic screens." (PMID 32346533, 2020). "Examples are mutations in the DNA repair gene BRCA2 in melanoma or in different stage IV cancers alterations in NOTCH, TERT, and NF1." (PMID 33353145, 2020).